EIF4E (eukaryotic translation initiation factor 4E)
Diseases named in the same sentence as EIF4E in open-access papers (continued):
Sharing a sentence is not in itself a finding about the gene and the disease.
cervical carcinoma (8 papers, 2002 to 2022). A carcinoma arising from either the exocervical squamous epithelium or the endocervical glandular epithelium. "First, a panel of cervical cancer cell lines was screened to evaluate the status of upstream proteins implicated in eIF4E regulation: two HPV‐positive (CasKi and HeLa) and one HPV‐negative (C33A) cell lines." (PMID 32981220, 2020). "The pharmacological inhibition of the PI3K/AKT/mTORC1 and MEK/ERK pathways underlined the contribution of both mechanisms to eIF4E phosphorylation in cervical cancer cell lines." (PMID 32981220, 2020). "In fact, quercetin, among other compounds, increases the susceptibility of cervical carcinoma cells to CD40L-induced apoptosis reversing CD40-mediated dissociation of the translational repressor eIF4E-binding protein from the initiation factor eIF4E." (PMID 21750559, 2011). "Likewise, strong staining of eIF4e is associated with high-grade cervical cancer." (PMID 31817792, 2019). "The oncoprotein E6 of HPV can activate the transcription factor eIF4E, and its inhibition in cervical cancer cell lines leads to CCND1 downregulation." (PMID 35468924, 2022). "The pharmacological inhibition of eIF4E phosphorylation by Ribavirin highlights the utility of this approach for the treatment of cervical cancer." (PMID 32981220, 2020). "The levels of TSP-2 and of eIF-4E mRNA were increased four- and seven-fold respectively in cervical cancer." (PMID 12189553, 2002). "Additionally, the overexpression of eIF4E has been found in breast, lung, prostate, colorectal, skin, head and neck, and cervical cancers, and elevated expression levels of eIF4E are strongly related to poor prognosis and decreased survival." (PMID 33148274, 2020). "We proceeded to investigate whether the altered regulation of CCND1 and ODC1 proteins by eIF4E was present in the cervical cancer cells." (PMID 32981220, 2020). "In our study, there was a seven-fold increase in transcript level of eIF-4E in cervical cancer." (PMID 12189553, 2002). "The differentiation of cervical cancer cells that are HPV‐positive augments the translation of E7 mRNA via the phosphorylation of 4EBP1 and eIF4E." (PMID 32981220, 2020). "The pharmacological inhibition of eIF4E phosphorylation through blocking of PI3K/AKT/mTORC1 and MEK/ERK highlights the utility of this approach for the treatment of cervical cancer." (PMID 32981220, 2020).
liver cancer (8 papers, 2012 to 2025). An epithelial or non-epithelial malignant neoplasm that arises from the liver. "Overexpression of eIF4E in invalids with liver cancer is associated with worse prognosis and high risk of recurrence." (PMID 36118897, 2022). "One of these genes, EIF4E, has already been reported in liver cancer, and other 27 are directly related to liver function." (PMID 29228658, 2017). "In liver cancer, DDX3X inhibits the eIF4E-eIF4G interaction by binding with eIF4E to repress global protein synthesis." (PMID 33627125, 2021). "In addition, from the PPI sub-network of the genes adjacent to the aberrant DNA methylation sites, we found that among the key genes with a gene node degree greater or equal to 10, MYC, EIF4E, CDK4 and TGFB1 could stimulate the pathogenesis of liver cancer." (PMID 26046465, 2015).
astrocytomas (7 papers, 2016 to 2022). "Furthermore, p-MKN1 levels were positively correlated with p-eIF4E levels, which in turn are associated with the grade of astrocytomas, tumor size, and unfavorable prognosis, and inversely correlated with overall survival rates." (PMID 32340135, 2020). "p-eIF4E and p-MNK1 overexpression was also associated with a decreased overall survival of patients with astrocytoma." (PMID 31795417, 2019). "Consistent with reports on these tumors, we observed overexpression of eIF4E in astrocytoma with respect to gliosis." (PMID 27440383, 2016). "Moreover, there are higher levels of p-MNK1 and its substrate p-eIF4E in astrocytoma tissues compared to normal brain tissues, which were associated with tumor recurrence." (PMID 32340135, 2020). "In our study, we found that NSCLC patients had high positive expression of p-mTOR and p-eIF4E proteins, which supports our previous findings in NPC and astrocytomas." (PMID 32023262, 2020). "Phospho (p)-eIF4E and p-4E-BP1 levels were increased during malignant progression in astrocytoma." (PMID 33807050, 2021). "Interestingly, expression of p-eIF4E is highly sensitive for the diagnosis of GBM (94.3%) and to a lesser extent for the differentiation between high-grade and low-grade astrocytomas (81.4%)." (PMID 31795417, 2019). "As for 4E‐BP1, eIF4E, and cyclin D1, expression in gliosis was significantly lower than in high‐grade DIA but not grade II astrocytoma." (PMID 27440383, 2016).
chronic myeloid leukemia (7 papers, 2016 to 2024). "Niclosamide inhibits the phosphorylation of the ERK, Mnk1, and eIF4E signaling pathways, and it also inhibits the proliferation of and induces apoptosis in chronic myeloid leukemia cells." (PMID 35008910, 2022). "The MNK-eukaryotic translation initiation factor 4E axis has been reported to activate β-catenin signaling in blast crisis chronic myeloid leukemia." (PMID 33929593, 2021). "Recently, our group reported that the Hsp70-Bim dimer recruits the oncogenic clients AKT, Raf-1, and eIF4E and mediates eIF2 signaling, the regulation of eIF4E and p70S6K signaling, and mTOR signaling pathway activation s to support chronic myeloid leukemia (CML) cell survival." (PMID 37237369, 2023).
fragile X syndrome (7 papers, 2017 to 2024). A genetic syndrome caused by mutations in the FMR1 gene which is responsible for the expression of the fragile X mental retardation 1 protein. "Hyperphosphorylation of eIF4E was implicated in brain diseases such as fragile X syndrome and its mouse model, the Fmr1−/y mice." (PMID 35481869, 2022). "CYFIP1 interacts with the Fragile X mental retardation protein (FMRP, encoded by the FMR1 gene), whose absence causes Fragile X syndrome, and with the translation initiation factor eIF4E." (PMID 28183735, 2017). "An increase in the levels of phosphorylated mTOR, S6K1, Akt as well as initiation factor 4E (eIF4E) has been observed in the protein lysates of individuals with fragile X syndrome." (PMID 36838876, 2023).
B-cell lymphomas (6 papers, 2012 to 2021). "Additionally, eukaryotic translation initiation factor 4E (eIF4E) overexpression led to the development of B cell lymphomas and facilitated lymphomagenesis." (PMID 33460399, 2021). "Recently, the CRM1 inhibitor selinexor has been approved by the FDA for the treatment of multiple myeloma, and the eIF4E inhibitor ribavirin has been shown to induce regression of aggressive B-cell lymphomas, both supporting the usability of cancer therapeutics targeting the CRM1 pathway." (PMID 32383752, 2020).
bladder cancer (6 papers, 2000 to 2025). "To further investigate the role of eIF4E phosphorylation in bladder cancer formation, we utilized the eIF4E S209 mutant mouse model (eIF4ES209A/+, eIF4ES209A/S209A)." (PMID 34032633, 2021). "Using murine and human models of advanced bladder cancer, we demonstrate that only tumors with high levels of eIF4E phosphorylation are therapeutically vulnerable to eFT508, the first clinical-grade inhibitor of MNK1 and MNK2, the upstream kinases of eIF4E." (PMID 34032633, 2021). "To determine if eIF4E phosphorylation is necessary for bladder cancer progression, we treated WT primary bladder cancer organoids with eFT508." (PMID 34032633, 2021). "Taken together, our data demonstrate that phospho-eIF4E levels in human bladder cancer organoids positively correlate with responsiveness to MNK1 and MNK2 inhibition." (PMID 34032633, 2021). "It is also known that eIF4E activity is essential for controlling proliferation and invasion in bladder cancer." (PMID 31119584, 2019). "Importantly, this work demonstrates that the functional target of eFT508 in bladder cancer is eIF4E and that inhibition of its phosphorylation is required for its therapeutic efficacy." (PMID 34032633, 2021). "Thus, eIF4E phosphorylation is required for bladder cancer progression and represents a potential biomarker for responsiveness to MNK1 and MNK2 inhibition in urothelial malignancies." (PMID 34032633, 2021). "Our results show that phospho-eIF4E plays an important role in bladder cancer pathogenesis, and targeting its upstream kinases could be an effective therapeutic option for bladder cancer patients with high levels of eIF4E phosphorylation." (PMID 34032633, 2021). "Given our observation that eIF4E phosphorylation is necessary for efficient bladder cancer formation, we next asked whether eIF4E phosphorylation is required for the maintenance of established tumors." (PMID 34032633, 2021). "eIF4E S209 phosphorylation is necessary for bladder cancer progression." (PMID 34032633, 2021). "As such, it is possible that more than one-third of patients with advanced stage bladder cancer may be good candidates for a therapeutic trial of an eIF4E phosphorylation inhibitor such as eFT508." (PMID 34032633, 2021). "eIF4E S209 phosphorylation is a requisite for a therapeutic response to eFT508 in bladder cancer." (PMID 34032633, 2021). "Furthermore, phospho-eIF4E plays an important role in bladder cancer progression, and targeting its upstream kinases could be an effective therapeutic option for bladder cancer patients with elevated phospho-eIF4E." (PMID 34032633, 2021). "In addition, one study suggests a role of androgen/AR signaling in phosphorylation of eIF4E, which can promote EMT in bladder cancer cell lines." (PMID 41463239, 2025). "Employing an eIF4E serine 209 to alanine knock-in mutant mouse model, we show that this single posttranslational modification is critical for bladder cancer initiation and progression, despite having no impact on normal bladder tissue maintenance." (PMID 34032633, 2021). "The study demonstrates that eIF-4E may be involved in translational regulation of VEGF in bladder cancer and might have a role as a prognostic factor in bladder cancer." (PMID 10638984, 2000).
cyst (6 papers, 2015 to 2026). A sac-like closed membranous structure that may be empty or contain fluid or amorphous material. "Immunofluorescence staining of whole organoids revealed the presence of both p-S6K1 and p-eIF4E within the cyst-like structures derived from FAP1 cells." (PMID 40702333, 2025). "As Pum levels diminish, this mode of regulation is handed over to Bru, which is robustly expressed from the 16-cell cyst onward, and its partner, Cup, which binds to eIF4E at the mRNA cap to mask pgc transcript from the translation initiation factors." (PMID 30590052, 2018). "We find that early expression of eIF4E-1 in the germ cells and the surrounding somatic cyst cells is essential for gonad morphogenesis and germline development." (PMID 25849588, 2015). "Taken together, our data supports a role of eIF4E-1 in early stages of spermatogenesis, showing that it is essential for germ cell cyst formation and germ cell differentiation." (PMID 25849588, 2015). "To examine whether eIF4E-1 is required in somatic cells for testes development, we expressed shRNA targeting eIF4E-1 in cyst cells using c587-Gal4." (PMID 25849588, 2015). "This suggests that eIF4E-1 is essential for somatic cell viability, and that germline differentiation does not proceed in the absence of proliferating cyst cells." (PMID 25849588, 2015).
depression (6 papers, 2018 to 2026). "Taken together, these results demonstrate that reduction of eIF4E phosphorylation, either by knocking out the Mnk1 and Mnk2 genes or by mutating the phosphorylation site in Eif4e, elicits depression- and anxiety-like behaviors." (PMID 29941989, 2018). "To further address the underlying mechanisms of eIF4E phosphorylation in the etiology of depression, we showed that eFT508 treatment significantly rescued LPS-induced depressive-like behaviors, neuroinflammation, and synaptic protein dysregulations in the mice." (PMID 37978167, 2023). "To understand the synaptic mechanisms underlying the depression-like state caused by inhibition of eIF4E phosphorylation, we first focused on serotonin (5-HT) neurotransmission in the medial prefrontal cortex (mPFC), a brain region central in depression pathophysiology." (PMID 29941989, 2018). "Moreover, the effects of eFT508 could be reversed by TrkB/BDNF antagonism, suggesting the critical role of eIF4E in the etiology of neuroinflammation-associated depression via TrkB/BDNF signaling." (PMID 37978167, 2023). "Thus, we reasoned that the pathways regulated by eIF4E phosphorylation could be linked to depression." (PMID 29367404, 2018). "Previous studies show that mice ablation of eIF4E phosphorylation demonstrated concomitant depression or anxiety-like behaviors." (PMID 37978167, 2023). "To illuminate the role of eIF4E activities within LPS-induced neuroinflammation and depression symptomology, we applied animal behavioral, biochemical, and pharmacological approaches." (PMID 37978167, 2023). "The link between phospho-eIF4E and depression is further strengthened by the fact that chronic fluoxetine treatment (10 mg/kg for 21 d) requires eIF4E phosphorylation to exert its antidepressant effect." (PMID 29367404, 2018). "Chronic fluoxetine treatment induced phosphorylation of eIF4E at Ser209 and alleviated depression-like phenotypes in mice." (PMID 29367404, 2018). "We show that phospho-eIF4E plays a previously unidentified role in the brain, whereby its depletion engenders depression-like behaviors and resistance to the chronic antidepressant action of the SSRI fluoxetine." (PMID 29367404, 2018). "Two recent studies revealed that mice with defective eIF4E phosphorylation (Mnk1/2-/- or Eif4eki/ki mice) show behaviors reminiscent of depression and anxiety, concomitant with increased inflammatory responses." (PMID 30532767, 2018). "We demonstrated that in mice, a deficit in eIF4E phosphorylation triggers depression and anxiety phenotypes, as well as reduced activity of DR neurons and impaired serotonin neurotransmission in the PFC." (PMID 29941989, 2018). "Together, these data establish a previously unidentified role for eIF4E phosphorylation in depression due to selective translation of a subset of mRNAs." (PMID 29367404, 2018). "While the connection between inflammation and depression is still under investigation, our data highlight a new translational control pathway, which may underlie the chronic antidepressant action of SSRIs and could be exploited to design novel antidepressants by boosting eIF4E phosphorylation." (PMID 29367404, 2018). "We reveal a novel role for eIF4E phosphorylation in inflammatory responses and depression-like behaviors." (PMID 29367404, 2018). "Control of pituitary mRNA translation is a novel function assigned to phospho-eIF4E; and apart from its link to depression, it will be important to examine its potential links to other neuropsychiatric or neurodevelopmental disorders or cancer (e.g., pituitary adenomas)." (PMID 29367404, 2018). "Given the convergence of these two pathways in the control of translation initiation, the question arises of how eIF4E function may affect or be affected by depression and anxiety disorders." (PMID 30532767, 2018).
depression (continued). "Hence, we hypothesized that the GABAergic system and eIF4E phosphorylation are involved in cognitive dysfunction and depression, particularly forms resistant to treatment, with increased aging." (PMID 41680149, 2026). "Moreover, K252a (TrkB/BDNF inhibitor) treatment could ablate the anti-depressive and anti-inflammatory activities of eFT508, suggesting the regulatory role of eIF4E in the synaptic processes via the TrkB/BDNF signaling during depression development." (PMID 37978167, 2023). "To gain insight into the molecular mechanism by which the lack of eIF4E phosphorylation results in depression-like behavior and altered serotonergic neurotransmission, we inspected the list of mRNAs whose translation is significantly reduced in the absence of eIF4E phosphorylation." (PMID 29941989, 2018). "In conclusion, phospho-eIF4E-dependent translation of GAIT element-containing mRNAs may constitute a unifying mechanistic explanation as to how dysregulated translational control of specific mRNAs could be causal for inflammation and depression, without affecting general translation." (PMID 29367404, 2018).
diabetes (6 papers, 2019 to 2025). "We leveraged the use of the PhenoScanner curated database to explore possible causal mechanistic associations between the circulating levels of EIF-4E and EIF-4A and type 2 diabetes mellitus." (PMID 32978410, 2020). "Similarly, it is well established that insulin resistance and co-morbid inability to properly regulate body weight and glucose homeostasis in diabetes involves the mTORC1/eIF4E pathway." (PMID 32722591, 2020). "The data suggest that higher circulating levels of EIF-4E (OR 0.94, CI [0.88, 0.99]) and EIF-4A (OR 0.90, CI [0.85, 0.97]) translation initiation proteins may be causally associated with a lower risk of type 2 diabetes mellitus." (PMID 32978410, 2020). "Our data indicated that the risk of diabetes varied with mTOR downstream target EIF-4E and EIF-4A, but not with RP-S6K or EIF4EBP2." (PMID 32978410, 2020). "The directionality of the MR association between circulating levels of EIF-4E and EIF-4A, mTORC1-dependent proteins, and type-2 diabetes mellitus was protection, i.e., higher circulating levels of EIF-4E and EIF-4A may be causally associated with decreased risk of type 2 diabetes mellitus." (PMID 32978410, 2020). "Out of these 15 predicted genes, we selected 4 target genes (IGF-1, SLC2a-12, EIF-4e, and ULK-2) based on the available literature related to myocardial function and/or diabetes for experimental validation." (PMID 30823517, 2019).
glioblastoma (6 papers, 2017 to 2025). The most malignant astrocytic tumor (WHO grade IV). "Knocking out MKNK1 can alleviate phosphorylated eIF4E and tumour formation in glioblastoma U87MG cells." (PMID 37864471, 2023). "For example, isoflavones induced the suppression of S6K phosphorylation in oestrogen receptor-positive breast cancer cells and decreased the phosphorylation of Akt and eIF4E proteins in human glioblastoma (U87) cells." (PMID 29179444, 2017).
lung adenocarcinoma (6 papers, 2012 to 2025). A carcinoma that arises from the lung and is characterized by the presence of malignant glandular epithelial cells. "Additionally, p-mTOR and p-eIF4E was dramatically higher in lung adenocarcinoma (both P<0.05)." (PMID 32023262, 2020). "Positive expression and distribution of p-Mnk1 and p-eIF4E were identified in the nucleus and cytoplasm of lung squamous cell carcinoma (SCC) and lung adenocarcinoma (ADC) tissues, respectively." (PMID 27050281, 2016).
multiple myeloma (6 papers, 2013 to 2022). "For instance, our research group has previously shown that G9a/GLP targeting in myeloma inhibits p-mTOR, followed by a decrease in p-4EBP1 and p-eIF4E, leading to MM apoptosis." (PMID 35105345, 2022). "Lenalidomide inhibits the translation of C/EBPβ by downregulating eIF4E, and IRF4 downregulation has been reported to be a critical factor controlling multiple myeloma survival and as a prognostic marker in patients with multiple myeloma associated with poor survival." (PMID 23420263, 2013).
Anxiety (5 papers, 2018 to 2024). Intense feelings of nervousness, tension, or panic often arise in response to interpersonal stresses. "Overexpression of eIF4E resulted in impaired motor function, anxiety-like behavior, and spatial exploration behavior in mice." (PMID 39557567, 2024). "Again, intracerebroventricular infusion of the eIF4E inhibitor, 4EGI-1, improved social behaviors and decreased anxiety." (PMID 35782388, 2022).